PTK2 (protein tyrosine kinase 2)
Diseases named in the same sentence as PTK2 in open-access papers (continued):
Sharing a sentence is not in itself a finding about the gene and the disease.
cancer (continued). "We then tested the effect of FAK inhibition in vitro on proliferation and the alteration of radiation sensitivity of cancer cell lines alone and in presence of stellate cells, using a PTK2 siRNA and a commercially available potent FAK-tyrosine kinase inhibitor, VS-4718." (PMID 32705304, 2021). "PTK2 inhibitors effectively inhibited cancer growth in vitro and in vivo." (PMID 31791326, 2019). "On the other hand, down-regulation of PTK2 expression can promote cancer cell anoikis." (PMID 29338725, 2018). "Cancer cells can escape anoikis by modulating PTK2 activity." (PMID 29338725, 2018). "However, a more recent WGS performed on 231 HCCs, as well as datasets available in cBioPortal for cancer genomics, showed that the amplification of the PTK2 gene is lower with respect of that already reported, ranging from 1.3% to a maximum of 15.6%." (PMID 28067792, 2017). "Other SRRM4 target genes such as PTPRF and PTK2, have known functions in regulating cell proliferation or apoptosis, suggesting that these genes may enable cancer cell to gain growth and survival advantages under chemo- or hormonal therapies." (PMID 28978002, 2017). "A number of known and previously unknown oncogenes were identified, some of which have already been reported to be associated with cancer, including: ADCY8, ZFAT, BAI1, PTK2, FBXL6, FOXH1, HSF1, and UGT2A1." (PMID 25372838, 2014). "PTK2 may be a prognostic marker and a novel molecular target for cancer treatment options." (PMID 31791326, 2019). "Combining natural selection, gene-based pathway analysis, and other associated analysis, we proposed that the pathway was significantly associated with PCa risk, in which the mutation of EGFR, ERBB2, PTK2, RAF1, and related SNPs in the genes might be the key link in the evolution of the cancer." (PMID 24223781, 2013). "Studies on the mechanism of action indicated a marked inhibition of the PTK2/FAK pathway, whose key role in tumorigenesis and in PDAC cancer progression and resistance is widely described." (PMID 40284015, 2025). "Among 36 genes, MMP1, HSP90B1, PTK2, MMP3, NOTCH1 and CDH5 had higher methylation status at pan-cancer level." (PMID 38694917, 2024). "The expression of PTK2, USP19, LAMC2, VEGFA, EPHA2, and MMP2 varies greatly among different cancer samples and has relatively high expression." (PMID 38694917, 2024). "For the analysis of survival probability, clinical data, and expression values for PTK2 and PTK2B genes (which code for FAK and Pyk2, respectively) in GBM tumors (provisional) were obtained from the cBioPortal for cancer genomics." (PMID 37686276, 2023). "Of note, an altered kinase signaling network involving EGFR, PDGFR, PAK1, PTK2 (FAK), PRKCD, and MAP2K2 appear to regulate the aberrant changes in the cancer cells and the TME accompanying recurrence." (PMID 35919862, 2022). "The expression levels of PLXNB1, PTK2, and IFI30 in the cancer group were lower than those in the normal group." (PMID 36211454, 2022). "In particular, focal adhesion kinase FAK(PTK2) caught our attention, because it is capable of conferring cell death resistance and to promote proliferation, migration and invasion of cancer cells." (PMID 35022419, 2022). "In cancer cells, signaling through S1PR1 leads to the activation of RAC1, SRC, PTK2/FAK1, as well as MAP kinases, and influences cell proliferation and survival in GBM." (PMID 34359681, 2021). "The results showed that the upregulated mrDEGs were enriched in several cancer-related pathways, such as MET activates PTK2 signaling, PI3K signaling, negative regulation of binding, and positive regulation of Wnt signaling pathway." (PMID 31959204, 2020).
cancer (continued). "ARRB2 and JAK3 were highly expressed in T cells, while PTK2 and ACTG1 were mainly enriched in the 'Cancer cluster." (PMID 32549766, 2020). "However, it is remarkable that FAK may affect E-cadherin expression in cancer cells by different mechanisms, suggesting that the pharmacological inhibition of FAK may counteract invasion and metastasis at least in cancers over-expressing PTK2 gene/protein." (PMID 28067792, 2017). "Some cancer-related genes are located in these highly common, early appearing RARs: MCL1, CTSK, ARNT, S100A10, PTK2, PTP4A3, and PSCA in the RAR-Gs; and DLC1, PINX1, and GATA4 in the RAR-Ls." (PMID 22938721, 2012). "Moreover, several genes, including PTK2, CCND1, and ERBB2, were identified as being closely related to the occurrence and progression of cancer, with their expression levels significantly correlating with patient prognosis." (PMID 40567661, 2025). "Thirdly, although technologies like CRISPR-Cas9 have been widely used in malignant tumor research, more gene editing methods should be employed in future explorations of the regulatory roles of LDH and PTK2 genes to delve deeper into their molecular mechanisms in APL." (PMID 40040719, 2025). "FAK (gene name PTK2) is a non-receptor tyrosine kinase that plays a role in regulating multiple cancer cellular functions, such as cell proliferation, migration, invasion and metastasis." (PMID 39271958, 2024). "First of all, this study showed that patients with low FAK/PTK2 expression are more responsive to immunotherapy, but the target molecules of FAK/PTK2 to regulate the immunotherapeutic response of cancer is unknown." (PMID 38518034, 2024). "PML, C3, TXN, KRT6C, F2, PTK2, TNF, which could enable HIF-mediated inflammatory response during cancer development." (PMID 36845724, 2023). "In addition, TBX15b also played a role in extracellular matrix (ECM)-receptor interaction, proteoglycans in cancer, and mesenchymal-epithelial transition (MET) activation of PTK2 signaling, PI3K-Akt signaling pathway, and immune system." (PMID 37328486, 2023). "Under DNA damage conditions, protein tyrosine kinase 2 (PTK2) phosphorylates ATG3 at the Tyr203 site and promotes the degradation of ATG3 through the ubiquitin-dependent proteasome pathway, resulting in positively regulating the activity of cancer cells." (PMID 35806307, 2022). "Notably, among the genes downregulated upon DSCAM-AS1 knockdown were several proliferation activators of endometrial (and other) cancer cells, like NOTCH1, HMGA2, PTK2/FAK, FOSL1, GREM1 and EGR1." (PMID 35885035, 2022). "Given that hematological malignancies represent a broad group of cancers we also determined whether co-expression of high CD80 and high PTK2 was restricted to particular hematological malignancies by subdividing this category based on origin." (PMID 31959281, 2020). "Moreover, we focused on the focal adhesion kinase 1 (FAK1), which is also called PTK2 protein tyrosine kinase 2 (PTK2) and known to increase cancer cell migration and promote metastatic dissemination to distant sites." (PMID 31731625, 2019). "PTK2 or focal adhesion kinase (FAK) is enriched in focal adhesions and together with Src kinase coordinates adhesion turnover, actin cytoskeleton dynamics and cell shape and regulates cancer cell migration and cell invasion." (PMID 31527453, 2019). "Furthermore, miR-106b-5p promotes the progression of CC by targeting three key genes (GSK3B, VEGFA, PTK2) through three crucial pathways (PI3K-Akt signaling pathway, focal adhesion, and pathways in cancer)." (PMID 30275981, 2018). "This region also contains some cancer related genes such as PTP4A3 and PTK2 genes." (PMID 27876019, 2016). "For early-stage cancers, DNA methylation-based biomarkers are of particular importance Recent scientific work indicates the high potential of hypermethylated genes TWIST1, VIM, ZNF671, OTX1, and IRF8 for early diagnosis and PTK2, AHNAK, and DAPK for BC prognosis." (PMID 39685620, 2024).
cancer (continued). "The DEGs were significant enriched in cancer associated pathways including surfactant metabolism, signaling by receptor tyrosine kinases, signaling by PDGF, non-integrin membrane-ECM interactions, MET activates PTK2 signaling, and so on." (PMID 33542901, 2020). "Focal adhesion kinase (FAK), a non-receptor tyrosine kinase, also known as protein tyrosine kinase 2, is a key regulator of growth factor receptor- and integrin-mediated signals, governing fundamental processes in normal and cancer cells through its kinase activity and scaffolding functions." (PMID 31558699, 2019). "The FAK, also known as protein tyrosine kinase 2 (PTK2), is a widely expressed nonreceptor tyrosine kinase that is a key component of the focal adhesion complex, which plays an important role in integrin and growth factor receptor signaling in both normal and cancer cells." (PMID 40725124, 2025). "CDK8, MET, PRKCZ, and PTK2 also exhibit negative scores against the majority of the cells, indicating inhibition of these hub genes could arrest cell proliferation required during cancer." (PMID 40500799, 2025). "In addition, PTK2 protein tyrosine kinase 2 (PTK2), phosphatidylinositol 3-kinase regulatory subunit gamma (PIK3R3), and phosphatidylinositol-4,5-bisphosphate 3-kinase catalytic subunit delta (PIK3CD) are shown to be related to pathways in cancer (KEGG ID: map 05200)." (PMID 30255812, 2018). "Protein tyrosine kinase 2 (PTK2) is both a non-receptor tyrosine kinase and an adaptor protein that governs fundamental processes in normal and cancer cells through its kinase-dependent or kinase-independent functions." (PMID 35154476, 2022). "Interestingly, while KDM4A and PTK2 have apparently never been considered for gene expression normalization, the consistent expression of EIF4H has been demonstrated in human cancer cells, where it was proposed as a reliable control gene." (PMID 33183298, 2020). "Moreover, by bioinformatics analysis based on The Cancer Genome Atlas (TCGA), we found the KCNMA1could regulate the expression of FAK (focal adhesion kinase), also named PTK2, which is a non-receptor tyrosine kinase and moderate cancer proliferation, migration and survival." (PMID 28231797, 2017).
infection (68 papers, 2011 to 2025). The state of being infected such as from the introduction of a foreign agent such as serum, vaccine, antigenic substance or organism. "Because PTK2 participates in the bacterial invasion pathway, hsa_circ_0085769 and hsa_circ_0002483 are probably associated with the osteogenic infection caused by S. aureus via interaction with their common miRNAs." (PMID 38560264, 2024). "On the other hand, gastric antral biopsies with infection of H. pylori iceA1/2+ strains showed a positive correlation with the ΔCt of the ptk2 gene (P < 0.005)." (PMID 36060520, 2022). "In a remarkable conclusion, this study showed that the gastric antral epithelial samples with infection of H. pylori iceA1/2 and cagE genotypes reveal a strong correlation with increased ptk2 gene expression (P < 0.001)." (PMID 36060520, 2022). "A defect in vacuolar escape for mutants lacking pheromone was further verified by observing that the ΔpplA mutants co-localized with Rab7 (a small GTPase associated with late endosomal vacuoles) at an early time point post-infection in infected PtK2 cells." (PMID 25822753, 2015). "In addition, a significant decrease of ΔCt of the ptk2 gene was revealed in patients with H. pylori cagE+ strains infection." (PMID 36060520, 2022). "We further determined that the decrease in FAK protein levels during Mtb infection occurs at the level of transcription as qRT-PCR analysis showed that mRNA transcript levels of PTK2, the gene encoding for FAK, decreased in a similar manner over the course of infection." (PMID 34745115, 2021). "Likewise, the Trefoil Factor Initiated Mucosal Healing pathways were significantly suppressed in early stage of infection, more specifically, PTK2, GHR, RHOA, CTNNB1, MAPK3, and SHC1 genes." (PMID 24349118, 2013). "Unlike T. caninum interaction characteristics, an interaction study between Trypanosoma copemani and PtK2 and Vero cells showed infection and interiorization of amastigotes, but no increase in the number of amastigotes or division was observed." (PMID 40225033, 2025). "In our study, both PTK2 and JAK1 were decreased at 12, 18, and 24 h after vvIBDV infection." (PMID 28086922, 2017).
adenocarcinoma (11 papers, 2010 to 2024). A common cancer characterized by the presence of malignant glandular cells. "Indeed, a detailed genomic analysis of chromosome 8q has been performed on gastroesophageal junction (GEJ) adenocarcinomas and this study revealed other genes (ANXA13MTSS1FAM84BC8orf17, and PTK2) except MYC involved in the 8q amplification and the pathology of GEJ adenocarcinomas." (PMID 22559327, 2012).
hematological malignancies (5 papers, 2017 to 2024). "PTK2 was only expressed in a subset of cell lines from hematological malignancies." (PMID 31959281, 2020).
neurodegenerative disease (5 papers, 2018 to 2024). A disorder of the central nervous system characterized by gradual and progressive loss of neural tissue and neurologic function. "PTK2 is closely associated with neuroinflammatory regulation and significantly influences the progression of neurodegenerative diseases." (PMID 39201475, 2024). "The pathological role of PTK2 was reported in several advanced-stage solid cancers, recently it is identified in ALS neurodegenerative disease also." (PMID 36590916, 2022).
blood cancers (2 papers, 2020 to 2024). "In addition to solid cancers, we also identified a number of hematological malignancies that co-express high levels of CD80 and PTK2, highlighting potential opportunities for the development of FAK inhibitors for the treatment of some blood cancers." (PMID 31959281, 2020).
PTK2 also shares sentences with these, for which no sentence is quoted: triple-negative breast carcinoma (48 papers); atherosclerosis (20); pancreatic ductal adenocarcinoma (20); leukemia (18); esophageal squamous cell carcinoma (16); head and neck squamous cell carcinoma (16); sarcoma (16); oral squamous cell carcinoma (14); lymph node metastasis (13); oral cancer (13); Sepsis (11); brain tumor (10); esophageal cancer (10); skin cancer (10); cardiac hypertrophy (9); Insulin resistance (9); renal cell carcinoma (9); cutaneous melanoma (8); Ewing sarcoma (8); head and neck cancer (8); multiple myeloma (8); pancreatic adenocarcinoma (8); renal carcinoma (8); serous ovarian cancer (8); chondrosarcoma (7); colorectal adenocarcinoma (7); fibrosis (7); medulloblastoma (7); nasopharyngeal carcinoma (7); adenoma (6).
A further 271 diseases each share a sentence with PTK2 in 6 papers or fewer.